RNU6-412P (RNA, U6 small nuclear 412, pseudogene)
Gene: Small nuclear RNA gene on chromosome 4 (46,531,237 to 46,531,342, reverse strand). Ensembl gene ENSG00000252243.
Homologues: Orthologues: chimpanzee U6 (100% identical), macaque U6 (92% identical). Paralogues in human: RNU6-1152P (87% identical), RNU6-1060P (86% identical), RNU6-15P (86% identical), RNU6-166P (86% identical), RNU6-19P (86% identical), RNU6-41P (86% identical), RNU6-949P (86% identical), RNU6-1011P (85% identical), RNU6-106P (85% identical), RNU6-1145P (85% identical), RNU6-12P (85% identical), RNU6-1316P (85% identical), and 1288 more.